TRMT6 (tRNA methyltransferase 6 non-catalytic subunit)
Diseases named in the same sentence as TRMT6 in open-access papers (continued):
Sharing a sentence is not in itself a finding about the gene and the disease.
ovarian carcinoma (3 papers, 2024 to 2025). A malignant neoplasm originating from the surface ovarian epithelium. "To delve into the mechanism by which TRMT6 influences the immune response in ovarian cancer, we conducted differential gene expression analysis based on the varying expression levels of TRMT6 and constructed a ceRNA network." (PMID 41244907, 2025). "We performed single-gene differential analysis of TRMT6 in the TCGA ovarian cancer database using the DESeq2 package and constructed a ceRNA network." (PMID 41244907, 2025). "We also found that in ovarian cancer tissues with high expression of TRMT6, the enrichment scores of T cells gamma delta (p < 0.01) and Mast cells activated (p < 0.05) were significantly lower than those in tissues with low expression." (PMID 41244907, 2025). "This study investigates the impact of the m1A regulator TRMT6 on prognosis and the tumor microenvironment in ovarian cancer." (PMID 41244907, 2025). "Correlation of the expression levels of TRMT6 with the clinicopathological characteristics of ovarian cancer patients." (PMID 41244907, 2025). "The TRMT6 gene worsens ovarian cancer prognosis by disrupting immune response pathways." (PMID 41244907, 2025). "Additionally, immunohistochemistry and the Log-rank test were employed to validate the impact of TRMT6 on the prognosis and clinicopathological characteristics of ovarian cancer patients." (PMID 41244907, 2025). "The findings suggest that the m1A regulator TRMT6 may drive ovarian cancer progression by promoting immune escape." (PMID 41244907, 2025). "Furthermore, we also found that in ovarian cancer tissues with high expression of TRMT6, the enrichment scores of T cells gamma delta(p<0.01)and Mast cells activated (p<0.05) were significantly lower than those in tissues with low expression." (PMID 41244907, 2025). "It is worth considering that TRMT6 may regulate the tumor immune microenvironment in ovarian cancer by interacting with HPSE, hsa-miR-17-5p, and lncRNA SNHG14." (PMID 41244907, 2025).
urothelial carcinoma of the bladder (2 papers, 2022 to 2023). "TRMT6/61A overexpression was also observed in urothelial carcinoma of the bladder, along with dysregulation of the tRF targetome." (PMID 37531210, 2023). "In urothelial carcinoma of the bladder, higher TRMT6/61A expression is accompanied by higher m1A modification on tRF-3b, accompanied by dysregulation of tRF targeted mRNAs." (PMID 35444240, 2022). "The TRMT6 upregulation is significant in urothelial carcinomas of the bladder (BLCA)." (PMID 35444240, 2022).
bladder (1 paper, 2022). "Interestingly, 8 out of the 9 tRF-3 targets repressed by siTRMT6/61A showed a significant positive correlation in expression with TRMT6 in TCGA bladder patient samples." (PMID 35444240, 2022).
colorectal cancer (1 paper, 2026). A primary or metastatic malignant neoplasm that affects the colon or rectum. "Moreover, TRMT6 is highly expressed in colorectal cancer (CRC), stabilizing the TRMT6-TRMT61A complex, enhancing the m1A modification of tRNA-Lys-TTT-1-1, and promoting histone translation with an AAA/AAG codon preference, thereby driving cell cycle and tumor progression." (PMID 41501031, 2026).
hepatoblastoma (1 paper, 2024). Hepatoblastoma (HB) is a malignant hepatic tumor and is the most common pediatric liver cancer. "Multivariate regression analysis demonstrated that three TRMT6 polymorphisms (rs236170 A > G, rs236188 G > A and rs236110 C > A) were significantly associated with susceptibility to hepatoblastoma." (PMID 37850543, 2024). "In this study, we investigated the association between four TRMT6 polymorphisms (rs236170 A > G, rs451571 T > C, rs236188 G > A and rs236110 C > A) and the risk of hepatoblastoma in a cohort of 313 cases and 1446 healthy controls." (PMID 37850543, 2024). "Our results demonstrated that three TRMT6 polymorphisms (rs236170 A > G, rs236188 G > A and rs236110 C > A) were able to modify hepatoblastoma risk in Chinese children individually." (PMID 37850543, 2024). "Stratification analysis of the association between TRMT6 genotypes and hepatoblastoma susceptibility." (PMID 37850543, 2024). "In conclusion, we identified three hepatoblastoma susceptibility SNPs of the TRMT6 gene." (PMID 37850543, 2024). "Four potential functional TRMT6 polymorphisms (rs236170 A > G, rs451571 T > C, rs236188 G > A and rs236110 C > A) were successfully genotyped and analysed for their contributions in hepatoblastoma susceptibility." (PMID 37850543, 2024). "In conclusion, we identified three susceptibility loci in the TRMT6 gene for hepatoblastoma." (PMID 37850543, 2024). "Besides, no studies have reported the associations between genetic polymorphisms of the TRMT6 gene and the risk of hepatoblastoma." (PMID 37850543, 2024). "Association of TRMT6 gene polymorphisms with hepatoblastoma susceptibility." (PMID 37850543, 2024). "This study aimed to interrogate whether genetic variants in the TRMT6 gene predispose to hepatoblastoma." (PMID 37850543, 2024). "Although different research teams confirmed the contributing role of TRMT6 in the carcinogenesis of HCC,4, 5 its impacts on hepatoblastoma are unknown." (PMID 37850543, 2024).
kidney papillary carcinoma (1 paper, 2025). "Finally, in kidney papillary carcinoma (KIRP), the signature included YTHDC2, IGF2BP2, DNMT3B, TRMT6, HNRNPC, and NSUN5." (PMID 40565233, 2025).
urothelial carcinoma of the (1 paper, 2022). "Lastly, we found TRMT6/61A expression is upregulated in urothelial carcinoma of the bladder relative to the normal bladder lining, and this is accompanied by higher m1A levels on tRF-3s and upregulation of tRF-3 targets that are enriched in the unfolded protein response." (PMID 35444240, 2022).
Wilms tumour (1 paper, 2025). "Notably, certain single nucleotide polymorphisms (SNPs) that are present in m1A writers (TRMT6), erasers (FTO), and readers (YTHDC1 and YTHDF2) have been associated with the risk of Wilms tumour risk, emphasising the significant role of m1A modification regulators in Wilms tumour development." (PMID 41017026, 2025).
tumor (17 papers, 2021 to 2025). "Given this, we investigated the role of TRMT6, an m1A regulator, in OC prognosis and the tumor immune microenvironment." (PMID 41244907, 2025). "Pan-cancer analysis revealed that RNA methylation genes ALYREF, NSUN4, TRMT6, and YTHDF1 were associated with immune infiltration in the tumor microenvironment." (PMID 41244907, 2025). "The ssGSEA algorithm and CIBERSORT were utilized to analyze the influence of TRMT6 on the tumor immune microenvironment." (PMID 41244907, 2025). "Then, we conducted in vivo experiments to verify the effects of overexpression and interference of TRMT6 on tumor growth." (PMID 36707905, 2023). "TRMT6 was overexpressed in HCC tissues and associated with Tumour-Node-Metastasis (TNM) stage, primary tumor (T) and regional lymph node (N) classification." (PMID 36707905, 2023). "The results showed that the tumor size was the largest in the TRMT6 overexpression group and the smallest in the interference group." (PMID 36707905, 2023). "IHC assay showed that the staining intensity of TRMT6 in Tumor group was significantly higher than that in Adjacent group." (PMID 36707905, 2023). "Immunohistochemistry analysis showed that the expression of WTAP, DNMT1, and DNMT3B in tumor tissues was significantly higher than that in paracancerous tissues, whereas the expression of TRMT6 was low in tumor tissues." (PMID 36203569, 2022). "Immunohistochemistry confirmed the high expression of WTAP, DNMT1, and DNMT3B in tumor tissue, but the low expression of TRMT6." (PMID 36203569, 2022). "Recently we reported m1A impedes tRF-3 gene-silencing activity and is over-expressed in BLCA tumor, coinciding with over-expression of the writer enzyme proteins TRMT6/61A and dysregulation of the tRF-3 targetome." (PMID 35923465, 2022). "There was a positive correlation between TRMT6 expression level and the overall m1A mismatch level of tRF-3b, and a significant increase of the m1A mismatch in the BLCA tumor samples that is consistent with the higher TRMT6/61A expression." (PMID 35444240, 2022). "Compared with the paracancerous tissues, the immunohistochemical results showed that the expression of TRMT6 was low in the tumor, and the other three genes were significantly higher, which was consistent with the results of the bioinformatics analysis." (PMID 36203569, 2022). "Of note, TRMT6 mRNA levels were dramatically elevated in HCC tumor tissues compared with adjacent peri-tumor tissues, which was further confirmed at their protein levels by immunoblotting." (PMID 34728628, 2021). "TRMT6 was significantly upregulated in 50–80% of HCC tumor tissues in our cohort of 191 HCC patients." (PMID 34728628, 2021). "Thiram displays effective suppression tumor growth in vivo, suggesting that thiram exerts its inhibitory antitumour effect through blockade of enzymatic activity of the TRMT6/TRMT61A complex." (PMID 34728628, 2021). "The abnormal expression of the m1A regulator TRMT6 may influence patient prognosis by exerting indirect or synergistic effects within the tumor immune microenvironment." (PMID 41244907, 2025). "It is essential to consider that TRMT6 may affect the prognosis of OC patients by participating in the regulation of tumor cell immune infiltration." (PMID 41244907, 2025). "TRMT6 regulates the malignant progression of TNBC by modulating ferroptosis in tumor cells." (PMID 41391019, 2025). "TRMT6 has displayed tumour‐promoting functions in several cancer types." (PMID 37850543, 2024). "Interference with TRMT6 inhibited tumor growth in vivo and was related to PI3K/AKT pathway." (PMID 36707905, 2023). "To explore the potential biological functions of m1A-dependent tRF-3 targets, we focused on biological pathways that are both significantly downregulated by siTRMT6/61A and significantly upregulated in high-TRMT6 tumor samples by Gene Set Enrichment Analysis of our RNA-seq data." (PMID 35444240, 2022).
tumor (continued). "To examine whether TRMT6/61A-mediated tRF-3 modification observed in cell line models is also seen in tumor samples, we obtained matched tumor and normal samples from clinically diagnosed BLCA patients, in which we confirmed by RNA-seq and RT-qPCR that TRMT6 RNA is over-expressed in tumor samples." (PMID 35444240, 2022). "TRMT6/TRMT61A affects all RNAs, influencing the proliferation and apoptosis processes in tumor cells." (PMID 39687616, 2024). "Among the regulatory genes, ALKBH1 and ALKBH3, which are methylation erasers, were upregulated and TRMT10C, TRMT6, TRMT61B, YTHDF2, and YTHDF3 were downregulated in tumor samples in comparison to normal tissues." (PMID 37679761, 2023). "Most importantly, dramatic upregulation of both TRMT6 and TRMT61A protein levels in tumor samples was detected by western blotting." (PMID 35444240, 2022). "Together, these data indicate that TRMT6/TRMT61A-mediated m1A modification enhances PPARδ protein translation, and PPARδ promotes liver CSC self-renewal and tumor growth." (PMID 34728628, 2021). "TRMT6 and TRMT61A, forming m1A methyltransferase complex, are highly expressed in advanced HCC tumours and are negatively correlated with HCC survival." (PMID 34728628, 2021). "Compared to the normal tissue, TRMT10C, TRMT6 and YTHDF2 were relatively highly expressed in the tumor tissue, while YTHDC1 was relatively less expressed." (PMID 34777359, 2021). "Consistent with our cohort, TRMT6 and TRMT61A levels were also remarkably increased in tumor tissues of Wang’s cohort and The Cancer Genome Atlas (TCGA) dataset." (PMID 34728628, 2021). "TRMT6 knockout HCC cells displayed compromised stemness properties, as reflected by impaired sphere formation and tumor initiating ability, and increased sensitivity to molecular target drug sorafenib." (PMID 33552715, 2021). "In terms of mRNA levels, TRMT6, TRMT61A, TRMT61B, TRMT10C, YTHDF1 and YTHDF2 YTHDF3 were overexpressed in tumor sample." (PMID 34777359, 2021). "We found higher protein and mRNA expression of TRMT6, TRMT10C and YTHDF2 in tumor samples." (PMID 34777359, 2021). "Notably, our research findings suggest a negative correlation between TRMT6 expression and the infiltration of various tumor immune cells." (PMID 41244907, 2025). "Furthermore, TRMT6 expression exhibited a significant negative correlation with eleven tumor-infiltrating immune cell types, including cytotoxic cells (p < 0.01)." (PMID 41244907, 2025). "The negative correlation (r < 0, p < 0.001) implies that TRMT6 may exert broad yet subtle regulatory effects on immune-infiltrating cells within the tumor microenvironment." (PMID 41244907, 2025). "At present, the effect of m1A modification on tumor is still in the stage of investigation, and it is not clear whether m1A methyltransferases such as TRMT6/61A can play a role by directly regulating the translation of target mRNA." (PMID 36707905, 2023). "In addition, we also detected the protein expression of TRMT6 downstream pathway-related proteins in tumor tissues, and the results showed that overexpression of TRMT6 could increase the expressions of p-PI3K, p-AKT and p-mTOR, while interference with TRMT6 had the opposite effect." (PMID 36707905, 2023). "Notably, Mut-TRMT6/TRMT61A overexpression could not rescue TRMT6/TRMT61A enhanced tumor growth." (PMID 34728628, 2021).
cancer (12 papers, 2018 to 2025). A tumor composed of atypical neoplastic, often pleomorphic cells that invade other tissues. "The TRMT6/61A complex is of great significance in a variety of biological systems, especially in the context of cancer." (PMID 40675967, 2025). "Elevated expression levels of TRMT6 have been observed in several cancers and often predict inferior prognosis." (PMID 37850543, 2024). "These mutations are associated with m1A regulators, including TRMT6, TRMT61A, TRMT10C, and YTHDF1, all of which also function as predictors of cancer risk." (PMID 38291517, 2024). "The expression of m1A regulators has previously been investigated in various cancers, and upregulation of TRMT6, TRMT61A, and ALKBH3 has been reported in BLCA." (PMID 38304034, 2023). "Many studies have found positive associations with m1A regulators, such as the m1A methyltransferase TRMT6, and cancer." (PMID 35350378, 2022). "ALKBH3 (p < 0.001), TRMT61A (p < 0.001), YTHDF1 (p < 0.001), ALKBH1 (p < 0.001), and TRMT6 (p < 0.001) in cancer tissues were significantly up-regulated compared to those in normal tissues (p < 0.001)." (PMID 34195072, 2021). "Dysregulation of TRMT6/TRMT61A has been reported in various cancers." (PMID 38304034, 2023). "The results showed that interfering with TRMT6 could inhibit the proliferation of cancer cells, the number of S phase cells and the protein expressions of p-PI3K, p-AKT and p-mTOR." (PMID 36707905, 2023). "Additionally, low expression of TRMT6 was observed in cancer tissues." (PMID 38291517, 2024). "Three m1A regulators (TRMT10C, TRMT6, YTHDF1) were significantly overexpressed in cancer tissues (p < 0.01)." (PMID 41244907, 2025). "In addition, we identified several novel oncogenic enzymes with up-regulation in multiple cancer types, including PUS1, a tRNA pseudoridylate synthase, and TRMT1 and TRMT6, the tRNA methyltransferases." (PMID 30588513, 2018). "According to the LIHC data set in the TCGA database, the expressions of TRMT6 gene in LIHC cancer tissues (n = 369) and paracancerous tissues (n = 50) were statistically analyzed, and it was found that TRMT6 was highly expressed in cancer tissues in the TCGA–LIHC data set." (PMID 36707905, 2023).
neurological diseases (1 paper, 2023). "In frontal cortex tissues from humans with AD, the gene expression of TRMT6, TRMT61A, TRMT10C, and YTHDF3 was consistent with that observed in our verification study, indicating that mRNA m1A methylation modification also plays a key role in human neurological diseases." (PMID 37173310, 2023).
TRMT6 also shares sentences with these, for which no sentence is quoted: colorectal adenocarcinoma (1 paper); digestive system neoplasm (1); Hypomagnesemia (1); lymph node metastasis (1); pancreatic cancer (1); triple-negative breast carcinoma (1).